CDKN2A (cyclin dependent kinase inhibitor 2A)
Diseases named in the same sentence as CDKN2A in open-access papers (continued):
Sharing a sentence is not in itself a finding about the gene and the disease.
ovarian carcinoma (77 papers, 1999 to 2025). A malignant neoplasm originating from the surface ovarian epithelium. "In ovarian cancer, previous studies showed that CDKN2A, the mutations of which led to loss of growth control in ovarian cancer cells, is related to the cell cuproptosis sensitivity, indicating that cuproptosis plays essential role in ovarian cancer." (PMID 38696071, 2024). "Among the FPC cohorts, ATM (3.09%) and BRCA2 (2.61%), two genes associated with breast and ovarian cancer, had the highest prevalence of PVs followed by CDKN2A (2.24%), the major high-risk susceptibility gene involved in familial melanoma." (PMID 34255164, 2021). "Overexpression of Ccnd1 is strongly correlated to decreased progression free survival and loss of Cdkn2a through mutation or hypermethylation has also been shown in human ovarian carcinomas." (PMID 24672774, 2014). "Upregulation of Ccnd1 and loss of Cdkn2a in STOSE tumors is consistent with changes identified in human ovarian cancers by The Cancer Genome Atlas." (PMID 24672774, 2014). "CDKN2B is a cell cycle control gene and several lines of evidence indicate that variants of these genes, particularly CDKN2A, are crucial in ovarian cancer." (PMID 23226780, 2012). "A significant positive association has been reported between CDKN2A expression and clinical outcome for epithelial ovarian cancer patients." (PMID 20842131, 2010). "CDKN2A methylation has been reported in association with poor prognosis in ovarian cancer." (PMID 38248716, 2023). "In our study, mutational analysis of TCGA ovarian cancer data has shown that a significant percentage of patients have mutations or dysregulated expression of CDKN2A, CDK4, CDK6, or CCND1 that would likely make them good candidates for CDK4/6 inhibitor therapy." (PMID 29644000, 2018). "In order to determine the role of CDKN2A in the development of sporadic ovarian cancer, loss of heterozygosity at 9p21–22, homozygous deletion, mutation and methylation status of the CDKN2A gene as well as CDKN2A expression were examined in a panel of serous papillary ovarian cancer." (PMID 10471040, 1999). "Although, previous studies have indeed explored aspects of cuproptosis mechanisms in ovarian cancer 59, they did not specifically highlight the importance of the cuproptosis-related gene CDKN2A in ovarian cancer." (PMID 40861807, 2025). "The results indicated that CDKN2A is likely a crucial factor in the development and progression of ovarian cancer." (PMID 40861807, 2025). "This study identified a single-base substitution of G for A in codon 148 of cyclin-dependent kinase inhibitor 2A (CDKN2A/p16) by sequencing human ovarian cancer cell line UACC-1598." (PMID 24944698, 2014). "Results of a recent study have indicated that the underexpression of certain cell cycle regulatory proteins, such as CDKN2A, is a predictive marker for shorter overall survival in ovarian carcinoma." (PMID 23226780, 2012). "C-MET enhances chemoresistance of human ovarian cancer cells, while the CDKN2A (p16) gene is a candidate for the tumor-suppressor gene, N-cadherin protein increases cell metastatic capacity, and finally P-glycoprotein/ABCB1 encodes drug transporter systems and activates multi-drug resistance." (PMID 38248100, 2023). "Besides, CDKN2A promoter methylation is a potential predictive factor for poor prognosis in ovarian cancer." (PMID 32992652, 2020). "Indeed, several types of cancer, including ovarian cancer, exhibit a methylation phenotype of CDKN2A." (PMID 32992652, 2020).
ovarian carcinoma (continued). "Interestingly, 21% of ovarian cancer patients showed CDKN2A deletions or significant downregulation." (PMID 29644000, 2018). "Similarly, a microarray analysis indicates that the cyclin‐dependent kinase 4 inhibitor A (p16INK4a) gene (CDKN2A) is upregulated in SALL2‐expressing versus SALL2‐null SKOV3 ovarian carcinoma cells." (PMID 29689621, 2018). "The TCGA array dataset was analyzed by the Cancer Genome Research Analysis Network and two of the top gene changes in the STOSE cell microarray were among those reported in the pathways most frequently altered in ovarian carcinomas: downregulation of Cdkn2a (−5.8) and overexpression of Ccnd1 (+6.2)." (PMID 24672774, 2014). "Therefore, we investigated the biological effect of the peptide aptamer Id1/3-PA7 in Id1/Id3-overexpressing and CDKN2A-positive ovarian cancer cells, ES-2 and PA-1." (PMID 20842131, 2010). "Interestingly, other authors have suggested that aberrant methylation of CDKN2A promoter may be essential to the initiation of ovarian cancer and in distinguishing malignant from healthy ovarian tissues." (PMID 32992652, 2020). "Finally, the in vitro and in vivo functional assays demonstrated that cuproptosis induced by CuET agent treatment could significantly inhibit ovarian cancer cell viability, migration and invasion as well as xenografted tumor growth where the CDKN2A expression level increased." (PMID 40861807, 2025). "The ratio of genomic alterations in CDKN2A and CDKN2B was also high in endometrial and ovarian cancers." (PMID 38201563, 2023). "Knock down of SMYD3 in ovarian cancer tissues leads to upregulation of CDKN2B (p15INK4B), CDKN2A (p16INK4), CDC25A and CDKN3 as members of cyclin-dependent kinase inhibitors (CDK)." (PMID 33333978, 2020). "Given that multiple previous reports have shown dysregulated cell cycle gene expression within the known CDKN2A/Cyclin D1-CDK4-CDK6/Rb axis, CDK4/6 inhibition represents a promising approach in ovarian cancer." (PMID 29644000, 2018). "By sequencing human ovarian cancer cell line UACC-1598, the present study also identified the CDKN2A/p16-A148T mutant." (PMID 24944698, 2014). "In summary, CDKN2A/p16-A148T was identified in ovarian cancer cells, and this single-base substitution did not affect the ability of CDKN2A/p16 to arrest the cell cycle." (PMID 24944698, 2014). "Interestingly, Cdkn2a is down-regulated in 30% of HGSC cases and Ccnd1 is amplified in 4% of the cases, according to TCGA ovarian carcinoma array." (PMID 24672774, 2014). "CDKN2A-negative ovarian cancer cells treated with a Mirk kinase inhibitor escaped G0/G1 quiescence, entered cycle with high ROS levels and underwent apoptosis." (PMID 23528858, 2013). "This could indicate that in PA-1 and ES-2 ovarian cancer cells, Id1/3-PA7 might preferentially inhibit the heterodimerisation of Id1 and Id3 with ETS proteins, which are the positive regulators of CDKN2A." (PMID 20842131, 2010). "Indeed, the kit we used, SOPHiA HCS, is more focused on hereditary breast and ovarian cancer, Lynch syndrome and intestinal polyposis syndromes, that do not include CDKN2A among the most relevant genes." (PMID 34034685, 2021). "The CDKN2A variant has previously been identified in COSMIC, however not in ovarian cancer." (PMID 28611940, 2017). "In contrast to CDKN2A, the methylation and mRNA expression of CDKN2B in ovarian cancer have not been extensively investigated." (PMID 23226780, 2012).
atherosclerosis (76 papers, 2009 to 2026). A disease characterized by the build-up of fatty material and calcium deposition in the arterial wall resulting in partial or complete occlusion of the arterial lumen. "PCBP2 activates p16INK4a via the functional SNP rs1333046 on the atherosclerosis‐associated CDKN2A/B locus." (PMID 41216990, 2025). "Recently, we have identified rs1333046 as one of the candidate functional single nucleotide polymorphisms (fSNPs) on the atherosclerosis‐associated CDKN2A/B locus." (PMID 41216990, 2025). "Our recent findings showed that CUX1 is an activator of p16INK4a, regulating p16INK4a-dependent cellular senescence via its binding to an atherosclerosis-associated fSNP rs1537371 on the CDKN2A/B locus." (PMID 38944813, 2024). "CUT-like homeobox 1 (Cux1) regulates p16INK4a-dependent cellular senescence in ECs and VSMCs by binding to atherosclerosis-associated functional SNP (fSNP) rs1537371 on the CDKN2A/B gene locus." (PMID 39519014, 2024). "Our findings that CTSL activates cellular senescence via an atherosclerosis-associated fSNP on the CDKN2A/B locus fully support the senescence theory in the development of atherosclerosis." (PMID 38944813, 2024). "Previously, we identified CUX1 as an activator of p16INK4a‐dependent cellular senescence in response to telomere shortening, DNA damage, and oxidative stress via its specific binding to an atherosclerosis‐associated fSNP rs1537371 on the CDKN2A/B locus." (PMID 36633253, 2023). "Post‐GWAS functional analysis reveals that CUX is a transcriptional activator of p16INK4a via its specific binding to a functional SNP (fSNP) rs1537371 on the atherosclerosis‐associated CDKN2A/B locus, regulating endothelial senescence." (PMID 36633253, 2023). "The monocyte-specific Cdkn2a deficiency has been previously reported to lead to accelerated atherosclerosis, induced pro-inflammatory gene expression, and increased proliferation of macrophages in mice." (PMID 36950286, 2023). "In particular, GWAS have repeatedly identified a 58 kb core region at the CDKN2A/B locus strongly associated with atherosclerosis." (PMID 34634809, 2022). "We demonstrate that this regulation occurs via the specific binding of CUX1 to an atherosclerosis-associated fSNP, rs1537371, on the CDKN2A/B locus." (PMID 37117763, 2022). "Our findings reveal a new role of CUX1 in regulation of cellular senescence and provide new insights into how genetic variants in the CDKN2A/B locus can modulate susceptibility to atherosclerosis and other age-related complications." (PMID 37117763, 2022). "For example, ANRIL and CDKN2A/B are closely associated with atherosclerosis (especially coronary arteries), while MIAT and LIPCAR play an irreplaceable role in myocardial infarction and heart failure." (PMID 35003390, 2021). "In line with these investigations, our study indicates an association between diminished expression of CDKN2A/2B/2BAS genes in leukocytes and increased atherosclerosis risk in T1DM." (PMID 31299986, 2019). "An atheroprotective function has therefore been suggested for these genes, since genetic inactivation of Cdkn2a variants in mice increases atherosclerosis and reduced expression of the transcripts has been found in atherosclerosis patients." (PMID 31299986, 2019). "Decreased expression of CDKN2A/2B/2BAS in leukocytes associates with increased CC-IMT atherosclerosis surrogate marker and proatherogenic CD14++CD16+ monocytes in T1DM patients." (PMID 31299986, 2019). "For example, whole-body deficiency of the other gene product of CDKN2A, i.e. p19ARF, aggravates atherosclerosis development in apoe−/− mice, although the exact mechanisms and cell types involved in vivo remained elusive." (PMID 22403661, 2012).
atherosclerosis (continued). "The animals were fed a western diet during 9 weeks and physiological parameters and atherosclerosis development were monitored, a time point comparable to the one where the effects of bone marrow CDKN2A-deficiency were observed." (PMID 22403661, 2012). "Our findings that oxLDL induces cellular senescence via an atherosclerosis-associated fSNP on the CDKN2A/B locus thus provide another possible mechanism that explains the role oxLDL may play in the pathogenesis of atherosclerosis." (PMID 38944813, 2024). "Recently, we demonstrated a role of CUT-like homeobox 1 (CUX1) in regulating the p16INK4a-dependent cellular senescence in human endothelial cells (ECs) and vascular smooth muscle cells (VSMCs) via its binding to an atherosclerosis-associated functional SNP (fSNP) rs1537371 on the CDKN2A/B locus." (PMID 38944813, 2024). "Several CDKN2A loss- or gain-of-function studies showed that this locus is involved in glucose homeostasis, β-cell functions (insulin secretion) and mass (proliferation), gluconeogenesis, atherosclerosis, and hepatic steatosis." (PMID 32971832, 2020). "Our study shows for the first time that increased atherosclerosis risk in T1DM patients associates with decreased expression of CDKN2A/2B/2BAS in leukocytes, which display pro-atherogenic phenotypes consisting of reduced circulating Treg cells and augmented proinflammatory CD14++ CD16+ monocytes." (PMID 31299986, 2019). "Cyclin-dependent kinase inhibitor 2A/2B (CDKN2A/2B) near chromosome 9p21 have been associated with both atherosclerosis and artery calcification, but the underlying mechanisms remained largely unknown." (PMID 27905995, 2016). "Genome‐wide association studies (GWAS) have identified a strong association of the locus for the cyclin‐dependent kinase inhibitor 2A/B (CDKN2A/B) with a multitude of age‐related diseases, including atherosclerosis and its related complications." (PMID 41216990, 2025). "From a functional perspective, CDKN2A and CDKN2B are functional candidate genes that are potentially implicated in the pathogenesis of atherosclerosis." (PMID 38149798, 2024). "Plays a key role in cellular aging, and in atherosclerosis models, the mRNA levels of CDKN2A are reduced." (PMID 39519014, 2024). "Genome‐wide association studies (GWAS) have validated a strong association of atherosclerosis with the CDKN2A/B locus, a locus harboring three tumor suppressor genes: p14ARF, p15INK4b, and p16INK4a." (PMID 36633253, 2023). "In particular, ANRIL is important for regulation of two tumor suppressor genes, cyclin-dependent kinase inhibitors A and B in CDKN2A/B locus that are involved in atherosclerosis in terms of thrombogenesis, vascular remodeling or repair, and plaque stability." (PMID 35186169, 2022). "Studies have shown that ANRIL regulates VSMC growth through CDKN2A/B (known as p16INK4A/p15INKB), which participates directly in the pathogenesis of atherosclerosis." (PMID 31011482, 2019). "In the present study, we found diminished mRNA expression levels of CDKN2A (p16Ink4a), CDKN2A (p14Arf), CDKN2B (p15Ink4b) and CDKN2BAS genes in circulating leukocytes of T1DM patients, who also displayed increased atherosclerosis risk measured as CC-IMT." (PMID 31299986, 2019). "Further studies are necessary to investigate the pathogenesis of atherosclerosis and vascular calcification and clinical utility of genes in 9p21.3 including CDKN2A and CDKN2B." (PMID 30921371, 2019). "And ANRIL, a lincRNA regulating CDKN2A and CDKN2B, was reported to be associated with atherosclerosis." (PMID 25628894, 2015).
atherosclerosis (continued). "Many of the genes identified are implicated in the regulation of SMC plasticity during atherosclerosis, including PDGFD, COL4A1/2, CDKN2B and CDKN2A/p19ARF." (PMID 23874238, 2013). "Combined with the recently published data showing that bone marrow-specific deletion of the complete CDKN2A locus promotes atherosclerosis development, our results exclude the involvement of solely p16INK4a." (PMID 22403661, 2012). "Finally, we find that CDKN2A expression (and by implication senescence) is low in human and mouse atherosclerosis and mouse carotid injury artery datasets compared with VSMC contractile and de-differentiated genes." (PMID 40493738, 2025). "Altogether, our study indicates an association between increased atherosclerosis in T1DM and reduced expression of CDKN2A/2B/2BAS in circulating leukocytes which displayed proatherogenic phenotypes such as enhanced proinflammatory monocytes and reduced Treg content." (PMID 31299986, 2019). "Both functional and genetic studies suggested that CDKN2A/2B may promote atherosclerosis by facilitating the process of calcification." (PMID 27905995, 2016). "Experiments using p19ARF bone marrow will show whether p19ARF alone or the combined deletion of both CDKN2A gene products in bone marrow-derived cells is required for influencing atherosclerosis progression." (PMID 22403661, 2012). "Overexpression of CDKN2A and CDKN2B in murine models is associated with pancreatic islet hypoplasia and diabetes, and there is also emerging evidence that vascular cell senescence involving these pathways is involved in the pathogenesis of atherosclerosis." (PMID 20386740, 2010). "Hence, decreased expression of CDKN2A/2B/2BAS genes in the present study could potentially contribute to the altered leukocyte phenotype and promote atherosclerosis in T1DM subjects." (PMID 31299986, 2019). "The effects of p16INK4a-deficiency on inflammatory phenotype thus appear insufficient to affect atherosclerosis or the development of obesity and glucose intolerance suggesting the involvement of other cell types, other gene products or combinations thereof in the CDKN2A/B genomic region." (PMID 22403661, 2012). "This region maps near two well-characterized tumor suppressor genes, CDKN2A and CDKN2B, encoding respectively proteins p16 INK4a and p15 INK4b, involved in the regulation of cell proliferation, cell aging and apoptosis, mechanisms that have a critical role in atherosclerosis." (PMID 20403154, 2010). "One example is the antisense non-coding RNA in the INK4 locus (ANRIL), residing at the 9p21 locus, which serves as a scaffold to regulate cyclin-dependent kinase inhibitor 2a/B expression, perpetuating atherosclerosis." (PMID 38291757, 2024). "In early-stage atherosclerosis, genes such as ATP7A, GLS, DLD, ATP7B, and PDHA1 are highly expressed, whereas in later stages, the expression levels of FDX1, CDKN2A, SLC31A1, and MTF1 increase." (PMID 39519014, 2024). "Expression data suggested a coordinated transcriptional regulation of ANRIL, CDKN2A and CDKN2B, and expression in tissues involved in atherosclerosis, like vascular endothelial cells, macrophages, and coronary smooth muscle cells, had been shown." (PMID 19214202, 2009). "Moreover, the expression of FOXP1 was positively correlated with SESN3 and negatively correlated with CDKN2A, MMP9, and ICAM1 in human atherosclerosis plaques." (PMID 41355963, 2026).